RAC1 (Rac family small GTPase 1)
Diseases named in the same sentence as RAC1 in open-access papers (continued):
Sharing a sentence is not in itself a finding about the gene and the disease.
cutaneous melanoma (continued). "The unfavorable outcome of patients with any genetic aberrations in RAC1 is in line with a report on the adverse prognostic significance of high RAC1 protein expression by immunohistochemistry in primary cutaneous melanoma samples." (PMID 30662871, 2018). "Indeed, in the context of cutaneous melanoma, reduced GTP biosynthesis is known to attenuate some of the transformation-associated phenotypes in a RAC1-dependent manner." (PMID 41154654, 2025). "Hotspot mutations in RQCD1, RAC1 and IDH1 were primarily in non‐acral cutaneous melanomas." (PMID 36219477, 2023). "In a small subset of cutaneous melanomas, and in the vast majority of uveal melanomas, the activation of PAK1 is expected as a consequence of activating mutations in the GNAQ and GNA11 oncogenes, which reportedly signal through RAC1 and RAS." (PMID 37830586, 2023). "Additionally, circZNF609 deficiency or overexpression in acral melanoma and cutaneous melanoma altered RAC1 expression at both the mRNA and protein levels, which was consistent with the RNA-seq results." (PMID 35534866, 2022). "Thus, targeting RAC1 represents a promising strategy for cutaneous melanoma therapy, as well as for inhibition of other signaling activation that promotes resistance to targeted therapies." (PMID 34827551, 2021). "Strikingly, although previous studies have revealed that FMRP might participate in RAC1 translation in mouse hippocampal neurons and Drosophila, our results confirmed that FMRP loss in acral melanoma and cutaneous melanoma could lead to increased RAC1 expression at the mRNA and protein levels." (PMID 35534866, 2022). "For instance, we have previously demonstrated that amplifying RAC1 signaling through overexpression of its GEF, VAV1, drives drug resistance to BRAFi in cutaneous melanoma." (PMID 36271142, 2022). "RIP assays showed that RAC1 mRNA was enriched in FMRP-IP groups in acral melanoma and cutaneous melanoma cells compared with IgG-IP groups." (PMID 35534866, 2022).
non-small cell lung carcinoma (19 papers, 2014 to 2025). A group of at least three distinct histological types of lung cancer, including non-small cell squamous cell carcinoma, adenocarcinoma, and large cell carcinoma. "Recent studies have found that the N,N′-disubstituted guanidino analog 1D-242 significantly inhibits RAC1-mediated TNFα-induced NF-κB nuclear translocation during non-small-cell lung cancer (NSCLC) cell proliferation and migration." (PMID 40723808, 2025). "The published article titled “miR-135a confers resistance to gefitinib in non-small cell lung cancer cells by upregulation of RAC1” has been retracted from Oncology Research, Vol." (PMID 40109867, 2025). "In non-small cell lung cancer, Rac1 is significantly up-regulated in tissues, while the knock-down of Rac1 can inhibit the invasion and migration of tumor cells and improve the sensitivity of cells to anticancer drugs." (PMID 35682879, 2022). "In particular, ECT2 acts as a nuclear GEF for RAC1 and drives tumor initiation of non-small-cell lung carcinoma through regulating rRNA synthesis." (PMID 32929379, 2020). "DOCK3 (a RAC1-GEF) has been shown to regulate cell adhesion in non-small cell lung cancer cells." (PMID 33057364, 2020). "Therefore, the present study provides novel insight into the complex cytotoxic and pro-survival mechanisms associated with a potent Rac1 agonist and suggests that further development of more potent Rac1 agonists could be an effective strategy for future non-small cell lung cancer treatments." (PMID 32578854, 2020). "Additionally, non - small cell lung cancer (NSCLC) - derived lncRNA - SOX2OT regulates osteoblast differentiation and stimulates bone metastasis by targeting the miRNA - 194 - 5p/RAC1 axis and the TGF - β/PTHRP/RANKL signaling pathway in osteoblasts." (PMID 40837012, 2025).
head and neck squamous cell carcinoma (17 papers, 2016 to 2025). A squamous cell carcinoma that arises from any of the following anatomic sites: lip and oral cavity, nasal cavity, paranasal sinuses, pharynx, larynx, and salivary glands. "Further supporting this mechanism, sodium bicarbonate cotransporter 3 (SLC4A7)PAK5 (P21 (RAC1) Activated Kinase 5) has been implicated in EMT induction and metastatic behavior in head and neck squamous cell carcinoma (HNSCC)." (PMID 40740483, 2025). "In a study of head and neck squamous cell carcinoma, integrin can regulate the activity of paxillin and downstream Rac1 through the FAK/Src complex to complete the cell migration process." (PMID 38791597, 2024). "ΔNp63α knockdown caused a significant elevation in Rac1-GTP levels in A431 epidermal SCC cells as well as in JHU-006 and JHU-009 head and neck squamous cell carcinoma (HNSCC) cells." (PMID 38191532, 2024). "In head and neck squamous cell carcinoma (HNSCC), Rac1 is involved in cell–matrix adhesion via fibronectin mediated by Ras-associated protein 1 (Rap1)." (PMID 37049739, 2023). "Rap1 plays an important role in cell-matrix adhesion and supports the key role of the RAP1/RAC1 signaling axis in head and neck squamous cell carcinoma (HNSCC) cell migration via inducing α5β1 integrin via the extracellular matrix molecule fibronectin." (PMID 35903698, 2022). "Simultaneously, in the Cancer Genome Atlas (TCGA) database, a subgroup of head and neck squamous cell carcinoma (HNSC, samples = 508) patients with favorable clinical outcomes showed infrequent copy number alterations that were correlated with activating mutations of HRAS, RAF, RAC1, and ERK1/2." (PMID 32419796, 2020). "A Rac1 inhibitor, which inhibited Rac1 activity, abrogated cell migration in head and neck squamous cell carcinoma cells (HNSCC)." (PMID 27791203, 2016). "In the treatment of head and neck squamous cell carcinoma (HNSCC), it was found that the combination of Rac1 inhibitors based on radiotherapy can improve the therapeutic effect." (PMID 34079763, 2021). "In head and neck squamous cell carcinoma (HNSCC), RAP1 has been found to play a prominent role in cell-matrix adhesion through the extracellular matrix molecule fibronectin-induced α5β1 integrin and in cell migration through the RAP1/RAC1 signaling axis." (PMID 33261656, 2020). "In addition, pharmacological inhibition of CCL2/CCR4/Vav2/Rac1/MLC signaling pathway can effectively reduce the motility of cancer cells, thereby inhibiting local invasion and distant lymph node metastasis in head and neck squamous cell carcinoma (HNSCC) cells." (PMID 41341593, 2025).
microcephaly (17 papers, 2013 to 2025). A congenital or acquired developmental disorder in which the circumference of the head is smaller than normal for the person's age and sex. "Variants in the TRIO GEF1 domain that decrease Rac1 activity are associated with milder ID and microcephaly, whereas variants in the adjacent spectrin repeat 8 domain that increase Rac1 activity are associated with more severe ID and macrocephaly." (PMID 40488445, 2025). "The striking correlation between RAC1 activation levels and the head size of the affected individuals has been shown; the active and inactive variants tend to be associated with microcephaly and macrocephaly, respectively." (PMID 35203342, 2022). "For example, deletion of Rac1 in the forebrain results in loss of neural progenitor cells, associated with increased cell-cycle progression and apoptosis, leading to microcephaly." (PMID 34572121, 2021). "Other genes within the combined network are involved in neuronal progenitor cell proliferation, a common mechanism underlying microcephaly (RAC1 and GNB1) and neuronal development (CEBPB, L1CAM, MAPT, PAK2, SPTBN1, and YWHAE)." (PMID 25781962, 2015). "Impaired activation of RAC1 is associated with microcephaly." (PMID 40988857, 2025). "Interestingly, missense mutations in Rac1 were recently identified to be associated with several human developmental disorders, including microcephaly, through dominant-negative effects of the Rac1 mutants on neuronal development." (PMID 34572121, 2021). "Interestingly, RAC1 deficiency in the forebrain of mice leads to a smaller forebrain resembling the microcephaly phenotype." (PMID 32109419, 2020). "Patients with ultra-rare RAC1 missense mutations have reported symptoms consisting of developmental delay, and macrocephaly, although some reported instances of microcephaly depended on whether the RAC1 mutation was a dominant negative activating or inactivating mutation." (PMID 37895289, 2023). "This aligns with observations in other genes, such as TRIO, where opposing Rac1 modulations result in either microcephaly (OMIM#617,061) or macrocephaly (OMIM#618,825)." (PMID 40019509, 2025). "Interestingly, microcephaly and macrocephaly also have been described in individuals harboring distinct variants in TRIO, a RAC1-GEF." (PMID 35203342, 2022). "For example, one study reported that Rac1 activates the pro-death mixed lineage kinase 3 (MLK3)-JNK kinase signaling pathway promoting neuronal cell death following cerebral ischemia, while in another study, Rac1 deletion from germinative zones determined microcephaly." (PMID 23734197, 2013). "Additionally, variants in the RAC1 gene (OMIM 602048) have been observed in patients with neuro‐developmental diseases, such as ID, which present in several phenotypic spectra, including microcephaly, cerebellar abnormalities, or macrocephaly." (PMID 32431071, 2020). "Considering the relationship of microcephaly with the PLEKHG2 variation, impaired RAC1-signaling might be partially related to the clinical features of the patients." (PMID 35203342, 2022). "Unlike Rac1-related MRD48, microcephaly is not common and macrocephaly has never been observed in affected individuals." (PMID 34943902, 2021).
Sepsis (17 papers, 2013 to 2025). Sepsis is defined as life-threatening organ dysfunction caused by a dysregulated host response to infection. "Several studies in rodent sepsis models showed involvement of Rac1 and/or RhoA GTPases in the development of sepsis-associated microvascular leakage and inflammation." (PMID 35634305, 2022). "The findings described in this review indicate that Rho proteins, mainly RhoA and Rac1, are associated with the development of crucial sepsis-associated dysfunction in different systems and cells, including the endothelium, vessels, and heart." (PMID 34440613, 2021). "The impaired activity of Rho-associated pathways, mainly increased activity of RhoA and the inhibition of Rac1, are listed in several studies associated with experimental sepsis models." (PMID 34440613, 2021). "Moreover, β-elemene was also suggested to treat sepsis-associated encephalopathy by regulating RAC1/MLK3/p38 signaling pathway." (PMID 35641589, 2022). "So there are human genetic polymorphisms in Rac1/LIMK1 that could predispose them to sepsis." (PMID 36686718, 2022). "Rac1, a gene associated with GLUT4 translocation and related to integrin signaling, was upregulated with sepsis (P < 0.001), and even further in Septic shFermt2 mice compared to Septic shControl mice (P < 0.01)." (PMID 41385533, 2025). "Here, the authors show that the duet hijacks calmodulin and Rac1, respectively, and transforms into a potent weapon to promote sepsis." (PMID 39043696, 2024). "Another study found that sepsis activates Rac1 in platelets, resulting in the secretion of CCL5 by the platelets." (PMID 38313013, 2024). "HULC knockdown has been shown to reverse LPS-induced sepsis via the regulation of miR-128-3p/RAC1 in HMEC-1 cells." (PMID 35615577, 2022). "Over-activated RAC1 is involved in pathological processes such as oxidative stress and inflammatory response upon sepsis." (PMID 31068775, 2019). "Moreover, drugs with direct effects on Rho proteins, including but not limited to RhoA, Rac1, and Cdc42, remain to be further explored in sepsis." (PMID 34440613, 2021). "By investigating the underlying mechanisms, the researchers found that Rac1 controlled surface mobilization of CD40L on activated platelets, so targeting Rac1 signaling might be a useful way to control the increased level of sCD40L in sepsis." (PMID 29780830, 2018). "In septic ZBED6‐deficient pigs, DOCK3 expression is increased in skeletal muscle and myocytes, activating the RAC1/PI3K/AKT pathway and protecting against sepsis‐induced muscle wasting." (PMID 37551034, 2023). "In contrast, skeletal muscles from sepsis patients with muscle atrophy showed significantly increased protein levels of ZBED6 and reduced levels of DOCK3/RAC1‐GTP/p‐AKT." (PMID 37551034, 2023). "ZBED6 deficiency increased DOCK3 expression, leading to hyperactivation of its downstream RAC1/PI3K/AKT signaling cascade, thus preventing sepsis‐induced muscle atrophy." (PMID 37551034, 2023). "During the early development of sepsis, the effect of thrombin is vascular disruption whereas at the later phase of sepsis, with increasing expression of PAR2, thrombin induces a vascular protective effect that is mediated by PAR2/Rac1 activation." (PMID 24860547, 2014). "Notably, sepsis patients show increased ZBED6 expression along with reduced DOCK3 and downregulated RAC1/PI3K/AKT pathway." (PMID 37551034, 2023). "Our study extended a protective role of DOCK3 in sepsis‐induced muscle atrophy and elucidated its upstream transcription factor ZBED6 and downstream RAC1/PI3K/AKT pathway, revealing a novel regulatory mechanism of DOCK3 underlying the occurrence of muscle atrophy." (PMID 37551034, 2023). "Therefore, we conclude that in contrast to the situation in sepsis, where LPS and TNF-α are relevant, alterations of cAMP levels as well as Rac1 activity are less important in anaphylaxis." (PMID 30185878, 2018).
Sepsis (continued). "Pharmacological activation of Epac1, selective enhancement of Rap1/Rac1 signaling, or targeted suppression of RhoA/ROCK during the repair phase could accelerate endothelial sealing in acute inflammatory conditions such as sepsis, acute respiratory distress syndrome, and ischemia–reperfusion injury." (PMID 41002641, 2025).
Alzheimer disease (16 papers, 2015 to 2025). A progressive, neurodegenerative disease characterized by loss of function and death of nerve cells in several areas of the brain leading to loss of cognitive function such as memory and language. "Misregulation of RAC1, causing alterations in neuronal cytoskeletal organization, has been implicated in neurodegenerative diseases, including Alzheimer’s disease." (PMID 37059183, 2023). "Emerging evidence indicates that dysfunctional Rac1 signaling is associated with Alzheimer’s disease (AD)." (PMID 37569255, 2023). "Rac1 signaling is also implicated in Alzheimer's disease, a neurodegenerative disorder characterized by neuronal loss in the hippocampus and cerebral cortex." (PMID 27442895, 2017). "In addition to psychiatric disorders, Rac1 is also associated with neurodegenerative brain disorders such as Alzheimer’s disease (AD)." (PMID 32362820, 2020). "Importantly, loss of TRPC6 expression leads to the activation of Rac1 in the kidney, which suggests that the lower expression of this channel observed in the brain of Alzheimer’s-disease patients could also promote the pathology by activating Rac1." (PMID 33240883, 2020). "We have recently shown that the Alzheimer’s disease (AD) therapeutic drug donepezil activates the Rac1-PAK pathway in the nucleus accumbens (NAc) for enhanced aversive learning." (PMID 37569255, 2023). "RAC1 splicing has been found to be altered in brains with Alzheimer’s disease and RAC1B expression in some neuronal populations in Alzheimer’s disease has been linked to increased neurofibrillary tangles and membrane dysfunction." (PMID 37059183, 2023). "A number of previous studies reported that Rac1 activity is increased in neurodegenerative disease, such as Alzheimer’s disease." (PMID 36406748, 2022). "The present study showed reduced α1-chimaerin expression in the brain of Alzheimer's disease cases, suggesting a role in the upregulation of Rac1 activity during the disease process." (PMID 25676811, 2015). "Rac1 activity is upregulated in Alzheimer's disease, but little is known about the role of α1-chimaerin." (PMID 25676811, 2015). "Rac1 overactivation is reported in human patients and animal models of Alzheimer’s disease (AD) and contributes to their spatial memory deficits, but whether Rac1 dysregulation is also important in other forms of memory deficits is unknown." (PMID 35936771, 2022). "The RAC1 gene could be a potential therapeutic target for preventing amyloid- β-induced neuronal cell death in Alzheimer’s disease." (PMID 33941241, 2021). "Moreover, upregulation of Rac1 appears to be important in driving the progress of Alzheimer’s-disease by promoting the production of the amyloid precursor protein and the amyloidogenic pathway." (PMID 33240883, 2020). "Thus, via enhancing APP production and cleavage, Rac1, likely, plays an important role in the formation of the amyloid-β plaques observed in Alzheimer's disease." (PMID 27442895, 2017). "Thus, this mode of Rac1 inhibition also represents a potential therapeutic avenue in Alzheimer's disease." (PMID 27442895, 2017). "We applied our computational framework to prioritize novel putative target genes for Alzheimer’s disease and successfully identified key genes that may serve as novel therapeutic targets (e.g., DLG4, EGFR, RAC1, SYK, PTK2B, SOCS1)." (PMID 33941241, 2021).